BDNF (brain derived neurotrophic factor)
Diseases named in the same sentence as BDNF in open-access papers (continued):
Sharing a sentence is not in itself a finding about the gene and the disease.
endometriosis (continued). "However, BDNF and TrKB expression in different stages of endometriosis and the relationship between the expression of each in ectopic lesions and endometriosis pain remain unclear." (PMID 35300713, 2022). "In addition, BDNF may be a key factor in chronic pelvic pain of endometriosis, and is an effector of estrogen in endometrial cells, thus affecting cell growth." (PMID 32210799, 2020). "However the clinical value of BDNF as a marker of endometriosis has also been challenged." (PMID 33214644, 2020). "The PF of endometriosis patients contains elevated levels of nerve growth factor (NGF), brain-derived neurotrophic factor (BDNF), and other neurotrophins such as NT-4 and NT-5." (PMID 40692689, 2025). "In fact, one of the most studied genes has been the brain-derived neurotrophic factor (BDNF), which has even been suggested as a neuronal biomarker for endometriosis diagnosis." (PMID 38339132, 2024). "The expression of BDNF and NTRK2 has been found to be significantly higher in the uterus of women with endometriosis than in healthy controls." (PMID 39062909, 2024). "We investigated the relationship between the endometriosis severity, IL-8, IL-10, BDNF, VEGF-A serum and tissue levels, patient-related pain, and physical activity in a cohort of 46 patients diagnosed with endometriosis who underwent surgery." (PMID 39202309, 2024). "BDNF and NTRK2 expression was significantly increased in the uterus of women with endometriosis compared with disease-free controls." (PMID 37509088, 2023). "Estradiol also stimulates macrophages to increase levels of brain-derived neurotrophic factor (BDNF) and neurotrophin (NT)-3, which promotes neurogenesis in endometriosis." (PMID 37834449, 2023). "In patients with endometriosis stages III and IV, the expression of BDNF in the ectopic endometrium was also higher than that in the eutopic endometrium (P < 0.05)." (PMID 35300713, 2022). "The concentrations of BDNF, NGF, and CGRP in DRG of the endometriosis group were significantly higher than these factors in the Control, Sham‐1, and RJ groups (p < 0.05)." (PMID 34806344, 2021). "Members of the NTs increasingly expressed in endometriosis include NGF, brain-derived nerve growth factor (BDNF) and neurotrophin 3 (NT3)." (PMID 30518376, 2018). "Moreover, it has been shown that the central nervous system’s microglia are highly active and release nerve growth factors (such as BDNF, NGF, and NT-3) that are involved in nociceptive sensitization in animal models of endometriosis." (PMID 40004233, 2025). "Brain-derived neurotrophic factor (BDNF), known for its involvement in neuroplasticity and neuronal survival, has emerged as a promising candidate, with studies demonstrating elevated levels in patients with endometriosis compared to healthy controls." (PMID 39062909, 2024). "One study found that initially, endometriosis patients had higher levels of BDNF in circulation than the control group of patients without endometriosis, and this finding was subsequently replicated by another group." (PMID 35300713, 2022). "In a clinical study, the serum BDNF level was significantly higher in patients with pain of endometriosis than in patients without pain." (PMID 33614695, 2021). "As research shows, BDNF is not useful in detecting peritoneal endometriosis and deeply infiltrating endometriosis." (PMID 34638893, 2021). "The concentrations of BDNF in plasma and PF are significantly greater in women with endometriosis than in women without endometriosis." (PMID 32145751, 2020). "One study found that there were no nerve cells in endometriotic lesions; however, BDNF and NGF could promote the generation of nerve tissue in endometriotic lesions, and the expression levels of BDNF and NGF were correlated with the degree of pain in endometriosis patients." (PMID 35300713, 2022).
endometriosis (continued). "First, several factors involved in nerve growth and found upregulated in women with endometriosis have been found to be regulated by E2, including nerve growth factor (NGF), vascular endothelial growth factor (VEGF), and brain-derived neurotrophic factor (BDNF)." (PMID 31387263, 2019). "In the present study, we aimed to measure the expression levels of BDNF and TrKB in the eutopic endometrium and ovarian endometriotic lesions of patients with endometriosis and to analyse the differences in expression among patients with and without endometriosis." (PMID 35300713, 2022). "A recent study demonstrated that targeting NGF therapy significantly reduced pain sensitivity in a mouse model of endometriosis, whereas inhibition of VEGFR1 and BDNF did not have analogous effects." (PMID 41301454, 2025). "Analysis of biomarkers IL-8, IL-10, BDNF, and VEGF-A was conducted in both the endometriosis group and the control group with non-endometriotic gynecological pathology." (PMID 39202309, 2024). "We performed correlation analyses between NGF and BDNF immunostaining and nerve fiber density (PGP9.5 staining) for both gland and stroma, and for the subtypes of endometriosis (PE and non-bowel DIE)." (PMID 27519317, 2016). "First, although no individual cut-off values were set, CA125 and BDNF levels were demonstrated to be elevated in patients with endometriosis, with CA125 mostly able to identify high-stage endometriosis and BDNF performing well for both low- and high-stage disease." (PMID 37509088, 2023).
sarcopenia (50 papers, 2016 to 2026). Progressive decline in muscle mass due to aging which results in decreased functional capacity of muscles. "Other studies have shown that circulating BDNF is associated with frailty and sarcopenia, yet the results are inconsistent." (PMID 40513379, 2025). "In the skeletal muscle, lower BDNF concentrations are linked to impaired muscle fibre repair and regeneration, increasing the likelihood of sarcopenia." (PMID 39937973, 2025). "Some scholars have suggested reasons from the perspective of mechanisms that sarcopenia can reduce muscle mass and strength, causing an imbalance in myokine secretion, including inflammatory cytokines, apelin, brain-derived neurotrophic factor, and chemokines." (PMID 40309867, 2025). "For example, Roh and co-workers showed that reduced plasma BDNF levels were associated with both sarcopenia and dementia in a cohort of community-dwelling adults aged 70–84." (PMID 38790190, 2024). "Although, in general, it seems that lower BDNF is associated with both sarcopenia and AD, it should be noted that expression of BDNF is modified by the presence of the rs6265 (G196A or Val66Met) variant within exon XI of the gene." (PMID 38790190, 2024). "Further study along these lines is required to elucidate the pathophysiological mechanism underlying the association between BDNF and sarcopenia severity." (PMID 37365209, 2023). "A Japanese study on hemodialysis patients revealed that low levels of BDNF were associated with a decrease in muscle function and an increased prevalence of severe sarcopenia." (PMID 36362238, 2022). "Low BDNF levels have been associated with decreased physical function and the prevalence of severe sarcopenia and frailty in Japanese patients undergoing maintenance hemodialysis." (PMID 35011721, 2022). "Physical inactivity caused by sarcopenia may result in reduced expression and low serum levels of brain-derived neurotrophic factor (BDNF) and insulin growth factor (IGF-1), which were reported to be associated with physical inactivity." (PMID 40400912, 2025). "Plasma BDNF concentration >1645 pg/ml was associated with 2.83 greater odds for sarcopenia (95%CI = 1.13-7.11, P = 0.027), than ≤1645 pg/ml, whilst a BDNF Z-score ≥2 was associated with 5.14 higher odds for sarcopenia (95%CI = 1.16-22.82, P = 0.031), than a Z-score <1." (PMID 39957555, 2025). "Moreover, in hemodialysis patients, low BDNF concentrations have been linked to reduced physical performance and increased risk of severe sarcopenia and frailty, reinforcing its potential as a biomarker of muscle health." (PMID 41441428, 2025). "The BDNF has been proposed as a biomarker for impaired memory and cognitive function in older women and elevated levels of IL-8 and sTNFr-1 have been linked to declining intrinsic capacity or sarcopenia in the older." (PMID 38684691, 2024). "Also, skeletal muscle tissue contraction releases brain-derived neurotrophic factor which regulates synapses in the brain, and its deficiency during sarcopenia is associated with neurodegenerative processes." (PMID 39240885, 2024). "In addition, BDNF, a neurotrophin growth factor essential for nervous system development and neuronal survival, has been associated with frailty and sarcopenia, and lower BDNF levels have been observed in patients with stroke." (PMID 37373767, 2023). "Similarly, our findings also revealed a possible association between BDNF levels and the severity of Sarcopenia." (PMID 37365209, 2023). "Indeed, the close association of irisin or BDNF levels with the sarcopenia index suggested that these myokines can be used as a reliable biomarker of sarcopenia and frailty." (PMID 33513795, 2021). "Notably, reduced BDNF serum concentrations were consistently observed in adulthood psychiatric pathologies, and both IGF-1 and BDNF levels have been associated with the development of sarcopenia." (PMID 29344422, 2017).
sarcopenia (continued). "Estrogen-dependent BDNF depletion may further strengthen the sarcopenia-cognition association." (PMID 40435122, 2025). "Additionally, an individual’s genetic background affects the expression and function of the BDNF gene; specific single nucleotide polymorphisms may lead to notable changes in BDNF activity, resulting in varying sarcopenia risks among different populations." (PMID 41140691, 2025). "This enables us to hypothesize that BDNF is implicated in the physiopathology of Sarcopenia and that its rise is related to muscle injury and impaired neuromuscular synaptic transmission caused by Sarcopenia and its progression." (PMID 37365209, 2023). "However, there is an age‐related loss of this effect of BDNF/TrkB signaling that may contribute to diaphragm muscle sarcopenia (atrophy and force loss)." (PMID 28082429, 2017). "In addition, this time course of aging effects whereby reduced BDNF availability precedes loss of TrkB receptor availability and the appearance of sarcopenia suggests a window of susceptibility to aging effects on the neuromuscular system and is of specific interest, warranting future investigation." (PMID 28082429, 2017). "Data regarding the relevance of brain derived neurotrophic factor (BDNF), a regulator of neuroplasticity, to sarcopenia in community-dwelling adults are scarce." (PMID 39957555, 2025). "The ameliorative effect of BDNF on aging sarcopenia involves muscle repair signal cascades and neuromuscular signaling connections." (PMID 40801027, 2025). "As additional biomarkers of sarcopenia and senescence, in a convenience sample of 100 enrolled subjects we will assess brain-derived neurotrophic factor (BDNF), a neurotrophin that plays a role in maintaining brain function." (PMID 40400914, 2025). "In turn, when sarcopenia develops, muscle activity diminishes, leading to a reduction in the release of myokines, which correspondingly lowers BDNF and irisin levels in the brain." (PMID 40677895, 2025). "In the defensive mechanism against sarcopenia, BDNF mainly ensures effective neural control over muscles by maintaining the integrity and function of the neuromuscular junction." (PMID 41140691, 2025). "In contrast, plasma BDNF levels are significantly lower in patients with aging sarcopenia and in debilitated patients with diminished muscle strength and physical activity." (PMID 40801027, 2025). "All these mechanisms support skeletal muscle regeneration; therefore, lower BDNF levels favour sarcopenia." (PMID 41010737, 2025). "Brain-derived neurotrophic factor (BDNF) levels predicted sarcopenia (cut off: 17.8 ng/mL) and reflected physical activity levels." (PMID 41464844, 2025). "A univariate analysis has verified the significantly lower levels of BDNF in patients with severe sarcopenia." (PMID 40014117, 2025). "Gait speed is an important marker of sarcopenia, and skeletal muscle is an endocrine organ that releases myokines (e.g. interleukin‐6, brain‐derived neurotrophic factor, tumour necrosis factor) to regulate inflammatory and metabolic pathways." (PMID 40275681, 2025). "The interplay of these mechanisms reveals the multiple roles of BDNF in muscle metabolism and neuromuscular adaptation, providing new research perspectives for the treatment of sarcopenia." (PMID 41140691, 2025). "Five independent studies indicate that the BDNF serum levels are significantly lower among patients with sarcopenia and frailty." (PMID 41010737, 2025). "The molecular mechanisms of BDNF action in muscle involve several key processes relevant to sarcopenia, including the regulation of satellite cell activity, myogenesis, and mitochondrial biogenesis." (PMID 41303670, 2025). "Among them, irisin and brain-derived neurotrophic factor (BDNF) are two substances regarded as potential biomarkers for sarcopenia." (PMID 41154577, 2025). "In a Japanese study of haemodialysis patients, BDNF concentrations were lower in subjects with severe sarcopenia and frailty." (PMID 38398421, 2024).
sarcopenia (continued). "Blood was drawn, and inflammatory biomarkers associated with Sarcopenia (IL-2, IL-4, IL-5, IL-6, IL-8, IL-10, TNF, adiponectin, leptin, resistin, BDNF, sTNFr-1 and sTNFr-2) was analysed." (PMID 37365209, 2023). "The analysis of inflammatory biomarkers revealed that the more advanced the stage of Sarcopenia, the higher the levels of BDNF, IL-8, sTNFr-1, and sTNFr-2." (PMID 37365209, 2023). "Taken together, the results of this study reveal for the first time that the greater the severity of Sarcopenia in older women, the higher the blood levels of BDNF, sTNFr1, sTNFr2, and IL-8." (PMID 37365209, 2023). "Specifically, we found higher levels of BDNF, IL-8, sTNFr-1 and sTNFr-2 as the sarcopenia severity increased." (PMID 37365209, 2023). "For instance, Myostatin and Irisin are directly involved in muscle metabolism and can be indicative of muscle atrophy, while BDNF and pro-inflammatory cytokines are linked to inflammation, a common underlying factor in both T2DM and sarcopenia." (PMID 37836433, 2023). "It should be emphasized that BDNF levels differed across all stages of Sarcopenia, demonstrating a correlation between the progression of Sarcopenia and BDNF production in community-dwelling older women." (PMID 37365209, 2023). "In this context, it was observed that the synthesis and release of BDNF in the brain can increase with physical activity, delaying the onset of sarcopenia." (PMID 36362238, 2022). "This protective effect is lost in sarcopenia as circulating BDNF, and GDNF levels decrease in advancing age in both genders." (PMID 34575696, 2021). "Another sarcopenia biomarker is brain-derived neurotrophic factor (BDNF), which induces the production of growth factors associated with differentiation, plasticity, and neuronal growth." (PMID 31457015, 2019). "Irisin and brain-derived neurotrophic factor (BDNF) are considered potential biomarkers for sarcopenia; however, their interplay and relationship with oxidative stress remain unclear." (PMID 41154577, 2025). "Notably, ROC analysis yielded an AUC of 0.712, with 17.8 ng/mL identified as the optimal BDNF threshold to diagnose sarcopenia." (PMID 41464844, 2025). "Perhaps we may speculate that BDNF delays skeletal muscle atrophy during aging by enhancing neuromuscular connections in patients with aging sarcopenia." (PMID 40801027, 2025). "Additionally, other myokines, such as interleukin 6 (IL-6) and brain-derived neurotrophic factor (BDNF), have been implicated in the modulation of sarcopenia." (PMID 40076821, 2025). "A lower BDNF concentration and a higher irisin-to-BDNF ratio may indicate a protective role of BDNF in the development of sarcopenia in geriatric patients; however, this finding requires further confirmation." (PMID 41154577, 2025). "A lower concentration of BDNF and a higher irisin/BDNF ratio in patients with dynapenia may indicate a protective role of BDNF in the development of sarcopenia in geriatric patients." (PMID 41154577, 2025). "However, in a recent study, BDNF levels were found to be elevated in community-dwelling older individuals with sarcopenia." (PMID 40513379, 2025). "There is also evidence of a link between the BDNF serum levels and sarcopenia." (PMID 41010737, 2025). "However, during the progression of sarcopenia, BDNF function is profoundly influenced by environmental and genetic factors." (PMID 41140691, 2025). "Based on these findings, sarcopenia is significantly related to lower BDNF levels in men, which may lead to altered functional connectivity in the DMN in the male population, potentially inducing tinnitus." (PMID 39014109, 2024). "In other studies, plasma concentrations of BDNF were higher in more advanced stages of sarcopenia." (PMID 38398421, 2024). "Taken together, these findings support the idea that dysregulated BDNF could be the potential link between sarcopenia and AD." (PMID 37577356, 2023).